PTPN2 (protein tyrosine phosphatase non-receptor type 2)
Diseases named in the same sentence as PTPN2 in open-access papers (continued):
Sharing a sentence is not in itself a finding about the gene and the disease.
cancer (63 papers, 2010 to 2026). A tumor composed of atypical neoplastic, often pleomorphic cells that invade other tissues. "Broadly speaking, mutation and amplification are the most common mutation types in PTPN2, accounting for all in some cancers." (PMID 37884566, 2023). "In this study, the expression and mutation status of PTPNs in pan-cancer were analyzed, finding that PTPN2 is working as a driver of AML." (PMID 37884566, 2023). "Overall, the evidence suggests that PTPN2 is a potential therapeutic target and diagnostic biomarker for specific cancers." (PMID 38022587, 2023). "In contrast, high PTPN2 function is associated with several cancers." (PMID 35911672, 2022). "However, as more and more comprehensive and detailed studies have emerged, PTPN2 has been implicated in cancer-promoting effects and poor prognoses." (PMID 36077422, 2022). "PTPN2 is also expressed ubiquitously and plays multiple roles in different cells so that the use of small inhibitors targeting PTPN2 in cancer might present the risk of causing additional side-effects." (PMID 33425916, 2020). "In addition, one study suggested that the loss of PTPN2 could improve the therapeutic efficacy of CAR-T cells in malignant tumors." (PMID 35154122, 2022). "In summary, we demonstrate that PTPN2 exerts cancer‐promoting effects by TFRC‐mediated mitophagy, a process that is independent of ferroptosis." (PMID 40734623, 2025). "With AC484, this study provides evidence that cancer immunotherapy with oral PTPN2/N1 systemic inhibitors is well tolerated and effective in multiple preclinical models, including those that are resistant to PD-1 blockade." (PMID 39065585, 2024). "Higher TIDE scores were observed in the PTPN2-high group, implying that increased PTPN2 expression in certain cancer types negatively impacted immunotherapy outcomes in patients." (PMID 38022587, 2023). "In this study, we sought to explore the efficacy and safety of small molecule inhibitors targeting PTP1B and PTPN2 in cancer." (PMID 37500611, 2023). "PTPN1 and PTPN2 have recently become attractive therapeutic targets in the context of cancer immunotherapy." (PMID 37581929, 2023). "We used TIMER2.0 to analyze the correlation between PTPN2 expression and immune cell infiltration in pan-cancer." (PMID 37884566, 2023). "We collected survival data from TCGA and TARGET data portals to evaluate the prognostic value of PTPN2 in pan-cancer using CoxPH and log-rank test." (PMID 37884566, 2023). "PTPN2 expression was found to be a reliable biomarker in a wide range of cancer types, and was significantly correlated with overall survival in AML." (PMID 37884566, 2023). "The results showed that the expression of PTPN2 was significantly positively correlated with RNA modified genes in most cancers." (PMID 37884566, 2023). "The expression of PTPN2 was significantly up-regulated in several cancers, it was significantly expressed in almost all types of cancer, especially LAML, ESCA, ALL, and CLL." (PMID 37884566, 2023). "Fraction Genome Altered (FGA) of PTPN2 in 30 types of cancer was detected, and the results indicated that shallow deletions are widespread in many cancer types." (PMID 37884566, 2023). "After a comprehensive evaluation on the expression patterns and immunological effects of PTPNs using a pan-cancer analysis based on RNA sequencing data obtained from The Cancer Genome Atlas, the most valuable gene PTPN2 was discovered." (PMID 37884566, 2023). "The results showed a significant positive correlation between PTPN2 expression and immunomodulatory genes in most types of cancer." (PMID 37884566, 2023). "PTPN2 mediates the generation of the Tim-3 subpopulation, and loss of Ptpn2 promotes the differentiation and formation of the Tim-3+CD8+ T cells and increases Tim-3+CD8+ T cell responses in MC38 cancer models." (PMID 37180158, 2023). "Previous studies have shown that inhibition of PTPN2 is a potential therapeutic strategy to improve the effectiveness of cancer immunotherapy." (PMID 37884566, 2023).
cancer (continued). "With AC484, we showed that oral administration of a PTPN2/N1 systemic inhibitor is a well-tolerated and effective cancer immunotherapy in multiple preclinical models, including those that are resistant to PD-1 blockade." (PMID 37794185, 2023). "Several observations correlate miR-155 expression with the JAK–STAT signaling pathway through the inhibition of SOCS1 and Ptpn2, suggesting its deep implication in inflammatory signal pathways and cancer." (PMID 38130990, 2023). "Then DEGs among groups were screened and subjected to GSEA to analyze the correlation between PTPN2 expression and cancer-related pathways." (PMID 37884566, 2023). "Here we present the discovery and characterization of AC484, a potent, orally bioavailable small-molecule inhibitor of PTPN2/N1 for cancer therapy." (PMID 37794185, 2023). "Since PTPN2 had the most potential TFs, we examined the correlation between the expression of PTPN2 and their potential TFs in 33 cancers." (PMID 36341348, 2022). "PTPN2 has also been shown to play an important role in T cell exhaustion, a state in which chronically stimulated T cells lose their ability to target cancer cells or chronic infections." (PMID 35911672, 2022). "A recent study showed that cancer cells can be sensitized for effective immunotherapy by sgRNA CRISPR-Cas9-mediated knockout of PTPN2, resulting in the upregulation of HLA class I surface molecules, similarly to what we observed for beta cells." (PMID 36497105, 2022). "Because of the different functions of PTPN2 in multiple cancers, the known literature cannot provide absolutely definite clinical treatment protocols utilizing PTPN2 as a cancer target." (PMID 36077422, 2022). "The other is in vivo genetic screening utilizing a CRISPR-Cas9 delivery system that identifies Ptpn2 as a cancer immunotherapy target." (PMID 36077422, 2022). "To determine the impact of PTPN2 expression in KRAS-related cancers, we analyzed clinical databases." (PMID 33122197, 2020). "We show that, for the first time, protein-tyrosine phosphatase non-receptor type 2 (PTPN2) regulates the KRAS plasma membrane association and plays an important role in KRAS-dependent cancer cell proliferation and survival." (PMID 33122197, 2020). "We separated KRAS mutation, KRAS expression, PTPN2 expression, and clinical information of KRAS-related cancers from TCGA cohorts." (PMID 33122197, 2020). "We discovered and characterized how disruption of DCAF15 or PTPN2 sensitizes a variety of cancer cell types to both NK-92 and primary NK cells." (PMID 31452512, 2019). "PTPN2 (protein tyrosine phosphatase, non-receptor type 2) has been recently identified as a novel cancer immunotherapy target." (PMID 29764444, 2018). "Twenty of these genes are located in 8q22–q24 and 17q21, including PAPBC1, RAD21, ATAD2, MTSS1, SQLE, ST3GAL1, C17orf37, ABCC3 and PTPN2, previously reported as cancer-related genes." (PMID 21339811, 2011). "PTPN1 and PTPN2 regulate cancer development and responses to immunotherapy." (PMID 38334623, 2024). "Because resistance to ICI therapy is observed in many solid tumors, we determined whether Ptpn2 inhibition sensitizes other cancers to IFNγ treatment." (PMID 36968224, 2023). "We have designed and evaluated small-molecule inhibitors of PTPN2 demonstrating that these compounds may have clinical utility as sensitizing agents for immunotherapy-resistant cancers." (PMID 36968224, 2023). "And PTPN2'riskscore can accurately predict the prognosis and response of cancer immunotherapy." (PMID 37884566, 2023). "Nonetheless, recent studies have defined the roles of PTP1B and PTPN2 in the immune system and their potential as targets for cancer immunotherapy and somewhat paradoxically, this has sparked interest in the development of drugs capable of targeting both PTP1B and PTPN26,7,10,11,14,21." (PMID 37500611, 2023).
cancer (continued). "Collectively, these results demonstrate that small-molecule inhibitors of PTPN2 may have clinical utility as sensitizing agents for immunotherapy-resistant cancers." (PMID 36968224, 2023). "This reveals the correlation between PTPN2 and cancer occurrence to a certain extent." (PMID 37884566, 2023). "PTPN2 is reported to regulate the activation of KRAS mutations, as well as the proliferation and survival of cancer cells, making it a potential therapeutic target for KRAS-mutant cancers." (PMID 36675641, 2023). "This suggests that PTPN2 expression potentially affects the RNA modification process in pan-cancer." (PMID 37884566, 2023). "Further studies suggested that PTPN7 significantly activated apoptosis, and EMT pathway in pan-cancer, PTPN2 significantly activated apoptosis and cell cycle pathway in pan-cancer, while PTPN21 significantly inhibited apoptosis and cell cycle pathway in pan-cancer." (PMID 37884566, 2023). "PTPN2 activates the JAK-STAT signaling pathway to promote cancer progression." (PMID 35957898, 2022). "PTPN2 levels are upregulated in human cancers that are refractory to current immunotherapy." (PMID 36077422, 2022). "Recently, PTPN2 has been identified as a potential target for cancer treatment." (PMID 35154122, 2022). "We next investigated the effect of PTPN2 on cancer cell growth, using pooled siRNAs to knockdown PTPN2 in a panel of five mutant KRAS-harboring human cancer cell lines (H460, PaTu8988T, HCT-116, A549, and DLD-1) and two KRAS wildtype human cancer cell lines (HT-1080 and SK-MEL-30)." (PMID 33122197, 2020). "Thus, PTPN2 expression is likely to be exploited as an attractive immunotherapy target in the treatment of cancer, such as STAD." (PMID 32536826, 2020). "In addition, somatic mutations in cancer cells, including loss-of-function mutations in JAK1/2, APLNR, PTPN2, and PBRM1, significantly correlate with the efficacy of cancer immunotherapies." (PMID 32244804, 2020). "We transfected cancer cells carrying KRAS-Q61K (H460) mutant with either control or PTPN2 siRNA." (PMID 33122197, 2020). "Moreover, recent CRISPR/CAS9 screening studies implicated other genes involved in regulating IFNy sensitivity as a cancer immunotherapy target, namely, tyrosine-protein phosphatase non-receptor type 2 (PTPN2) and apelin receptor (APLNR)." (PMID 31196219, 2019). "PTPN2 has been proposed to have a suppressive role in cancer." (PMID 31025094, 2019). "While PTPN2 blockade could be used as a monotherapy target, it could also increase the sensitivity of other ICIs in the treatment of patients with cancer." (PMID 29764444, 2018). "We speculate that high PTPN2 expression level is an adaptive mechanism of cancer immunosurveillance, as we found a higher number of infiltrating antitumor immune cells." (PMID 29764444, 2018). "Furthermore, PTPN2 transcript levels are upregulated in human cancers that are refractory to current immunotherapy." (PMID 29764444, 2018). "PTPN2 plays a dual role in development and progression of cancer." (PMID 28400551, 2017). "Therefore, 44 RNA modification regulators of three types of cancer-related RNA modifications were collected, including N6-methyladenosine (m6A), N1-methyladenosine (m1A), and 5-methylcytosine (m5C), and the correlation with PTPN2 expression was analyzed." (PMID 37884566, 2023). "In addition, studies have shown that PTPN2 deficiency might enhance the therapeutic effect of CAR-T cells in malignant tumors, therefore, we can combine PTPN2 small molecule inhibitors with immunotherapy drugs to obtain a better therapeutic effect on tumors." (PMID 35154122, 2022). "The results indicate that PTPN2 may be a novel therapeutic target for KRAS-driven cancers." (PMID 33122197, 2020).
cancer (continued). "Our data suggest that PTPN2 could serve as a potential therapeutic target for KRAS-driven cancer." (PMID 33122197, 2020). "Among the 14 other TSG candidates, except PTPN2/TCTP none has been so far associated with cancer." (PMID 20698951, 2010). "The most recent PTPN2 and PTP1B active-site inhibitor, ABBV-CLS-484 (AC484), is the first active-site phosphatase inhibitor to enter clinical evaluation for cancer immunotherapy." (PMID 39065585, 2024). "A plethora of studies have demonstrated that PTPN2 and PTP1B (PTPN2/N1) contribute to the aggressiveness of cancer by modulating key pathways and molecules such as PTEN, Src activation, and the PKM2/AMPK/mTOC1 pathway." (PMID 39065585, 2024). "For example, PTPN2 (also known as TC-PTP) and its paralogue, PTPN1 (also known as PTP1B), are centrally positioned within cancer development and antitumor immunity, with a wide array of cellular functions attributed to them." (PMID 39065585, 2024). "In a recent study, a related compound of the PTPN1/PTPN2 inhibitor ABBV-CLS-484, Compound-182, showed promise in small animal models for cancer therapeutics." (PMID 37766318, 2023). "By obtaining subcellular localization of PTPN2 in the HPA, PTPN2 was found in the nucleoplasm and was highly expressed in almost all cancer cell lines including SiHa, U-2 OS, U-251 MG, A-431, and CACO-2." (PMID 37884566, 2023). "An orally bioavailable small-molecule active-site inhibitor of the phosphatases PTPN2 and PTPN1, ABBV-CLS-484, demonstrates immunotherapeutic efficacy in mouse models of cancer resistant to PD-1 blockade." (PMID 37794185, 2023). "Inhibitors of PTPN2 and PTPN1 offer a promising new strategy for cancer immunotherapy and are currently being evaluated in patients with advanced solid tumours (ClinicalTrials.gov identifier NCT04777994)." (PMID 37794185, 2023). "Genome-wide CRISPR screens of a broad panel of mouse cancer cell lines, including B16F10 and MC38, have shown that that Ptpn2 and other negative regulators of the IFNγ response are involved in immune evasion by multiple cancer types." (PMID 36968224, 2023). "SHP2, ITK, VRK2, PTPN2, GSK-3, CDK4/6, and PAG all have evidence supporting their relationship to the PD-1 pathway in T cells and pro-tumorigenic role in cancer cells." (PMID 35911672, 2022). "The literature discussed here was obtained from a search of the published literature and ClinicalTrials.gov with the following key terms: checkpoint inhibition, cancer immunotherapy, PD-1, PD-L1, SHP2, PTPN2, ITK, VRK2, CDK4/6, GSK-3, and PAG." (PMID 35911672, 2022). "In summary, reducing the level of PTPN2 in cells can markedly reduce the malignancy of PAAD, suggesting that PTPN2 plays critical roles in regulating PAAD and is a potential target to develop novel anti-cancer drugs." (PMID 35154122, 2022). "In accordance with the previous studies, STAT3 acts as a possible target of PTPN2 by dephosphorylation and the levels of p‐STAT3 are dramatically elevated in various cancer cell lines." (PMID 32285621, 2020). "Furthermore, a correlation between PTPN2 transcript levels and immunosuppressive cells, such as neutrophils, MDSCs, and Tregs, was observed, with neutrophils, MDSCs, and Tregs exhibiting strong immunosuppressive activities and contributing to poor clinical outcomes in patients with cancers." (PMID 29764444, 2018). "Here, we report that head and neck squamous cell cancer (HNSCC) exhibits a mechanism of STING suppression related to upregulation of protein tyrosine phosphatase non-receptor (PTPN) type 2 (PTPN2) that is also evident in other cancers." (PMID 42069723, 2026). "Like PTPN2, PTPN1 regulates STAT5-dependent signalling in T cells, whilst the deletion of PTPN1 enhances the efficacy of CD8+ conventional T cell and CAR-T cell ACT in mouse models of cancer." (PMID 38334623, 2024).
cancer (continued). "PTPN2, a non-receptor type 2 protein tyrosine phosphatase, plays a vital role in both the development of tumors and the field of cancer immunotherapy as an immune checkpoint." (PMID 38214842, 2024). "PTPN2 was also found to be widely correlated with ESTIMATE score, immune score, and stromal score in pan-cancer The findings indicated that PTPN2 played a vital role in immune infiltrates in pan-cancer and has the potential to serve as a response indicator in clinical practice." (PMID 37884566, 2023). "To explore the therapeutic potential of targeting PTP1B and PTPN2 in cancer with a small molecule inhibitor, we took advantage of AbbVie’s/Calico’s Compound 182, which inhibits both PTP1B and PTPN2 and is related to the small molecule drug ABBV-CLS-484 currently in clinical trials." (PMID 37500611, 2023). "Protein tyrosine phosphatase non-receptor type 2 (PTPN2) was recently identified as a novel cancer target." (PMID 35935861, 2022). "In this study, we discussed the critical roles of PTPN2 in regulating PAAD, which could be used as a valuable target to design and develop effective small molecule anti-cancer drugs." (PMID 35154122, 2022). "A CRISPR–Cas9 based in vivo screen identified protein tyrosine phosphatase non-receptor type 2 (PTPN2) as a novel immunotherapy target in cancer." (PMID 30636933, 2019). "Overall the top three enriched targets in the cluster can be classified into immunomodulation, which are PTPN2, protein kinase C beta type (PKC-β), protein kinase C eta type (PKC-η), and protein kinase C gamma type (PKC-γ), cancer, namely, TOPO1, and glucose homeostasis, such as SGLT2." (PMID 26989424, 2016). "In summary, these results report PTPN2 as a negative prognostic factor in cancer." (PMID 29764444, 2018). "Knockdown of PTPN2 reduced the proliferation and promoted apoptosis in KRAS-dependent cancer cells, but not in KRAS-independent cells." (PMID 33122197, 2020). "Thus, PTPN2 knockdown significantly reduced proliferation and promoted apoptosis in KRAS-dependent cancer cells (HCT-116, PaTu8988T, and H460), but not in KRAS-independent cells." (PMID 36077422, 2022).